SMAD4 (SMAD family member 4)
Diseases named in the same sentence as SMAD4 in open-access papers (continued):
Sharing a sentence is not in itself a finding about the gene and the disease.
astrocytic tumor (1 paper, 2025). A glial tumor of the brain or spinal cord showing astrocytic differentiation. "Figure 2illustrates the promoter methylation status of six genes involved in the TGF-β signaling pathway—SKIL, SMAD1, SMAD3, SMAD4, BMP2, and MAPK1—across astrocytic tumors of increasing malignancy (grades G2, G3, and G4)." (PMID 40869118, 2025).
astrocytomas (1 paper, 2025). "In this study, we present multi-level evidence demonstrating that key mediators of the TGF-β signaling pathway—SKIL, BMP2, SMAD1, SMAD3, SMAD4, and MAPK1—are consistently upregulated in high-grade astrocytomas." (PMID 40869118, 2025).
atrial fibrillation (1 paper, 2012). A disorder characterized by an electrocardiographic finding of a supraventricular arrhythmia characterized by the replacement of consistent P waves by rapid oscillations or fibrillatory waves that vary in size, shape and timing and are accompanied by an irregular ventricular response. "Ang II can enhance the expression of TGF-β1, P-SMAD2/3 and SMAD4, which may serve as a key mechanism underlying atrial fibrillation (AF)-induced atrial fibrosis." (PMID 23185428, 2012).
auditory neuropathy (1 paper, 2023). A hearing disorder characterized by impaired transmission of signals through the auditory nerve, resulting in mild to severe hearing loss and poor speech perception. "Similarly, conditional knockouts of Smad4 display disruption of ribbon synapses and auditory neuropathy." (PMID 37885485, 2023).
bladder adenocarcinoma (1 paper, 2025). "This novel approach has revealed that urachal adenocarcinoma is associated with specific gene mutations, including RAS, GNAS, SMAD4, and BRAF, which are absent in bladder adenocarcinoma." (PMID 39778497, 2025).
brain injuries (1 paper, 2017). "HA protects neurons from traumatic brain injuries, and this could be related with HA-mediated disappearance of Hyal-2, which reduces the WWOX/Smad4 signaling." (PMID 27845895, 2017).
cataract (1 paper, 2018). Partial or complete opacity of the crystalline lens of one or both eyes that decreases visual acuity and eventually results in blindness. "Snail is considered an effector of TGF-β-induced EMT and it is activated by TGF-β signaling through the action of p-Smad2/3 and Smad4 in mouse lens epithelial cells; consistent with these reports, we also observed increased expression of Snail mRNA in K14E6 cataracts." (PMID 29888254, 2018).
cerebral infarction (1 paper, 2022). An ischemic condition of the brain, producing a persistent focal neurological deficit in the area of distribution of the cerebral arteries. "Compared with those of sham operation and control groups, mRNA levels of ALDH1, Smad2, and Smad4 were markedly higher in cerebral infarction group, whilst p21 level was lower (P < 0.05)." (PMID 35909581, 2022).
cervical intraepithelial neoplasia (1 paper, 2007). "Furthermore, Smad4 expression was lost in 10 of 41 primary squamous cervical carcinomas and reduced in 26 cases as shown by immunohistochemistry, whereas all cervical intraepithelial neoplasias (CIN) retained normal Smad4 expression levels." (PMID 17997817, 2007).
chronic asthma (1 paper, 2024). An asthma that is characterized by the development of persistent airway inflammation and recurrent attacks of breathlessness and wheezing, which vary in severity and frequency. "In another study of a chronic asthma rat model treated with resveratrol, the phosphorylated SMAD2 and SMAD4 levels were reported to be decreased, but no change was observed in SMAD7 protein expression." (PMID 39055873, 2024).
Cirrhosis (1 paper, 2024). A chronic disorder of the liver in which liver tissue becomes scarred and is partially replaced by regenerative nodules and fibrotic tissue resulting in loss of liver function. "In human tissue microarray (TMA) analysis, Smad4 expression significantly increased in cirrhosis and HCC specimens compared with healthy liver specimens." (PMID 39346534, 2024).
congenital heart disease (1 paper, 2021). A heart disease that is present at birth. "We selected miRNAs for each of SMAD4 (hsa-miR-421 and hsa-miR-454-3p) and PTEN (hsa-miR-107 and hsa-miR-320a-3p) for binding validation since the four miRNAs have been reported to have important association with heart development or congenital heart disease." (PMID 34046402, 2021).
cryptorchidism (1 paper, 2017). The failure of one or both testes of a male fetus to descend from the abdomen into the scrotum during the late part of pregnancy. "In the present study, non-synonymous SNPs in both BMP8B and SMAD4 loci were found to be common to all patients with CAKUT accompanied by cryptorchidism, suggesting that impairment of the BMP/SMAD signaling pathway was likely involved in the pathogenesis of this condition." (PMID 29197384, 2017). "Besides, MAF of SNPs in SMAD4 and FREM2 (rs2496423) is lower than 1%, suggesting that these rare variants is possibly pathogenic for CAKUT accompanied with by cryptorchidism." (PMID 29197384, 2017). "Both BMP8B and SMAD4 function in the same signaling pathway, and it is likely that this pathway is involved in the etiology in CAKUT accompanied by cryptorchidism." (PMID 29197384, 2017).
cystic tumors (1 paper, 2013). "Targeted Smad4 inactivation in the mouse pancreas does not initiate tumorigenesis, however concomitant Smad4 loss and KRASG12D expression leads to the rapid development of PanIN lesions and cystic tumors." (PMID 24386371, 2013).
dementia (1 paper, 2023). Loss of intellectual abilities interfering with an individual's social and occupational functions. "However, it is important to note that the exact mechanisms of SMAD4’s involvement in dementia, including any direct or specific functions it might have, are complex and still being studied." (PMID 37759801, 2023).
dilated cardiomyopathy (1 paper, 2022). Cardiomyopathy which is characterized by dilation and contractile dysfunction of the left and right ventricles. "In addition, loss of SMAD4 is associated with disease progression and poor prognosis in many tumorigenic diseases, and loss of SMAD4 causes cardiac dysfunction and dilated cardiomyopathy." (PMID 36060794, 2022).
dry eye (1 paper, 2023). "Several genes of the hippo pathway, including YAP1, TEAD1, or SMAD4, were down-regulated in patients with dry eye." (PMID 38254630, 2023).
Endometrial Intraepithelial Neoplasia (1 paper, 2019). A premalignant neoplastic process that affects the endometrial epithelium and glands. "Our findings show a potential diagnostic role of this microRNAs signature for the accurate diagnosis of Endometrial hyperplasia with atypia/Endometrial Intraepithelial Neoplasia and improve the understanding of their pivotal role in SMAD4 regulation." (PMID 31293968, 2019).
ependymoma (1 paper, 2019). A WHO grade II, slow growing tumor of children and young adults, usually located intraventricularly. "The specific variants we found in the present ependymoma case such as inTP53, HRAS, SMAD4, PIK3CA are not in TCGA projects." (PMID 32612806, 2019).
gastrointestinal adenomas (1 paper, 2017). "Animal studies have shown that SMAD4 inactivation is involved in the malignant transformation of gastrointestinal adenomas and a reduction in SMAD4 mRNA levels has been observed during tumor progression." (PMID 29290978, 2017).
glaucoma (1 paper, 2023). Increased pressure in the eyeball due to obstruction of the outflow of aqueous humor. "The down-regulation of miR-1298 in glaucoma pathology contributes to TGF-β2/Smad4 pathway and TM injury." (PMID 37940950, 2023).
glomerulosclerosis (1 paper, 2018). A hardening of the kidney glomerulus caused by scarring of the blood vessels. "AMPK activation has been shown to inhibit the upregulation of Smad4 and reduce glomerulosclerosis." (PMID 29966331, 2018).
HIV-1 infection (1 paper, 2020). The type species of lentivirus and the etiologic agent of acquired immunodeficiency syndrome (AIDS). "Furthermore, our data suggest a potential link between IFNβ, decreased TGFβ signaling (SMAD4), increased unfolded protein response (VIMP and SEP15) and increased DNA damage (NUP54 and MUS81) in chronic HIV-1 infection." (PMID 33064743, 2020).
hydronephrosis (1 paper, 2014). Collection of urine in the renal pelvis that results in dilatation of the renal pelvis and calyces. "In this study, we found loss of Smad4 in the ureteral mesenchyme led to failure of SMC differentiation, resulting in severe hydroureter and hydronephrosis during mouse embryogenesis." (PMID 25127126, 2014). "Mice with genetic deletion of Smad4 in ureteral mesenchyme displayed hydroureter and hydronephrosis as early as E16.5, and the mutant mesenchymal cells failed to differentiate into SMCs at E15.5." (PMID 25127126, 2014). "A recent study has attempted to disrupt Smad4 with Tbx18-Cre transgenic line, and the mutant embryos displayed hydronephrosis at E17.5." (PMID 25127126, 2014). "We found that mice with specific deletion of Smad4 in Tbx18-expressing ureteral mesenchyme exhibited hydroureter and hydronephrosis at embryonic day (E) 16.5, and the mutant mesenchymal cells failed to differentiate into SMCs with increased apoptosis and decreased proliferation." (PMID 25127126, 2014).
Hyperammonemia (1 paper, 2023). An increased concentration of ammonia in the blood. "Shared DAP that were increased at both 6 and 24 h of hyperammonemia included Eif4b, Map4, Arpc1b, Eif3b, S100a4, Smad4, and Hist1h2bb." (PMID 37101412, 2023).
hypogonadal (1 paper, 2014). "Deletion of the Type II activin receptor as well as gonadotrope-specific knockdown of both SMAD4 and FOXL2 resulted in a hypogonadal hypogonadism phenotype reminiscent of the Fshb knockout." (PMID 25423188, 2014).
hypopharyngeal carcinoma (1 paper, 2023). Carcinoma, predominantly squamous cell, arising from the epithelial cells of the hypopharynx. "It is unclear how SMAD4, which promotes favorable clinical outcomes and antitumor immunoregulation, along with CD8+ cytotoxic T cells and CD15+ neutrophils exert an influence on hypopharyngeal carcinoma (HPC)." (PMID 37035326, 2023).
ischemic stroke (1 paper, 2023). A stroke disorder caused by obstruction of blood flow to the brain, due to thrombotic (local blood clot formation) or embolic (due to a blood clot or other material traveling from another site) event. "SMAD4 has been implicated in inflammation and hypercoagulation in ischemic stroke, has been associated with BBB disruption and in our previous study was up-regulated in IS participants who later developed hemorrhagic transformation." (PMID 36691064, 2023).
juvenile idiopathic arthritis (1 paper, 2023). Juvenile idiopathic arthritis (JIA) is the term used to describe a group of inflammatory articular disorders of unknown cause that begin before the age of 16 and last over 6 weeks. "Similarly, with DCVs in the MH2 domain, Ménétrier’s disease, hypertrophic osteoarthropathy and juvenile idiopathic arthritis have been seen in this population, whereas cardiac pathologies have occurred both alongside and independently of SMAD4 + JPS with DCVs in the MH1 domain." (PMID 38066625, 2023).
juvenile polyposis coli (1 paper, 2021). "A third disease-causing mutation has been found in the SMAD-4 gene, causing a combination of HHT and juvenile polyposis coli." (PMID 33801690, 2021).
Kaposi's sarcoma (1 paper, 2021). A malignant neoplasm characterized by a vascular proliferation which usually contains blunt endothelial cells. "In Kaposi's sarcoma-associated herpes virus infection, viral IFN regulatory factor 1 inhibits TGF-β pathway via its direct interaction with both SMADad3 and SMAD4 and through the prevention of their transactivation activity." (PMID 33546553, 2021).
lentivirus infection (1 paper, 2024). Virus diseases caused by the Lentivirus genus. "To further examine the role of Smad4 in regulating macrophage polarization, we knocked down Smad4 in Raw264.7 cells using lentivirus infection to establish a Smad4 knockdown (Sh-Smad4) Raw264.7 cell line." (PMID 39664586, 2024).
macrosomia (1 paper, 2015). "Therefore, regulation of SMAD4 by miR-19a, miR-19b and miR-20a may play an important role in the development of macrosomia." (PMID 26598317, 2015). "Expression levels of SMAD4, SMAD3, RB1 and EP300 genes were significantly decreased in placentas of neonates with macrosomia compared with those of controls." (PMID 26598317, 2015).
malignant pancreatic neoplasm (1 paper, 2013). A malignant neoplasm involving the pancreas. "SMAD4 is a tumor suppressor gene on chromosome 18q21.1 that is inactivated in >50% of pancreatic malignancies, and SMAD4 protein overexpression suppresses cell proliferation in malignant pancreatic neoplasms." (PMID 23833648, 2013).
mammary adenocarcinomas (1 paper, 2009). "Apc+/1572T/Smad4+/Sad mice show a similar incidence of mammary adenocarcinomas similarly to Apc+/1572T, but are characterized by multiple GI-tract tumors." (PMID 19578404, 2009). "Accordingly, Apc+/1572T/Smad4+/Sad compound heterozygous mice revealed a similar incidence of mammary adenocarcinomas as in Apc+/1572T, but were also characterized by multiple GI-tract tumors never observed in the parental strain, even when kept for longer than 1 year." (PMID 19578404, 2009).
mesenchymal tumors (1 paper, 2022). "Thus, using two different approaches to identify tumors with strong evidence for EMT, we could show that SMAD4 mutations are not less frequent in mesenchymal tumors of the colon and the pancreas." (PMID 34857888, 2022). "To further corroborate SMAD4-independence of mesenchymal gene expression by a second approach to define mesenchymal tumors that was not related to the CMS classification, we performed single-sample GSEA (ssGSEA)." (PMID 34857888, 2022).
Ménétrier’s disease (1 paper, 2023). "Given association with extracolonic polyposis and higher GI cancer risk, endoscopic screening should occur more frequently and at an earlier age in SMAD4 + JPS patients than in patients with other causative genes, with consideration of Ménétrier’s disease on upper GI endoscopy." (PMID 38066625, 2023).
microphthalmia (1 paper, 2016). Congenital or developmental anomaly in which the eyeballs are abnormally small. "Previous research has shown that deletion of Smad4 in the lens ectoderm of mice leads to severe abnormality in the anterior segment and microphthalmia." (PMID 27494603, 2016). "We found that specific deletion of Smad4 in the surface ectoderm leads to microphthalmia, consistent with a recent report." (PMID 27494603, 2016). "Consistent with a previous publication, microphthalmia was observed in the Smad4-cKO mice." (PMID 27494603, 2016).
multiple endocrine neoplasia type 1 (1 paper, 2024). An autosomal dominant tumor predisposition syndrome caused by pathogenic variants in the MEN1 gene, characterized by an increased risk of tumors of the parathyroid glands, pituitary gland, and foregut neuroendocrine tumors (most commonly pancreatic islet cells). "Notably, one patient with an APC gene mutation also harbored a SMAD4 (SMAD family member 4) gene mutation, while another patient with a SMAD4 gene mutation (n = 2, 14.29%) concurrently presented with a MEN1 (Multiple Endocrine Neoplasia Type 1) mutation (n = 1, 7.14%)." (PMID 39162366, 2024).
multiple myeloma (1 paper, 2015). "Treatment with PS341, a proteasome inhibitor clinically used to treat multiple myeloma, showed some accumulation of nuclear SMAD4." (PMID 26258650, 2015).
myelofibrosis (1 paper, 2022). A partial or complete replacement of the bone marrow stroma by fibrous tissue. "Induction of myelofibrosis by MPLW515L was intact in Osx-Cre Smad4fl/fl recipients, demonstrating that SMAD4-independent TGF-β signaling mediates the myelofibrosis phenotype." (PMID 35439167, 2022). "Canonical (SMAD4-dependent) TGF-β signaling in MSCs is not required for MPLW515L-induced myelofibrosis." (PMID 35439167, 2022). "Deletion of Smad4 in bone marrow MSCs does not prevent the induction of myelofibrosis by MPLW515L." (PMID 35439167, 2022).
neoplastic polyp (1 paper, 2021). "The presence of the same SMAD4 mutations in both CRC and neoplastic polyp (264, 386, 435, c.484-4) suggests that these mutations had occurred in the primary polyps, and then the cell population having these mutations gained the potential and permission to develop into carcinoma." (PMID 35154600, 2021).
neuroendocrine carcinoma (1 paper, 2019). A malignant neuroendocrine neoplasm composed of cells containing secretory granules that stain positive for NSE and chromogranin. "We identified an association of SMAD4 mutations with mucinous morphology, advanced tumor stage, concomitant RAS mutations and divergent differentiation in a rare mixed adenocarcinoma and neuroendocrine carcinoma." (PMID 30730996, 2019).
ovarian mucinous adenocarcinoma (1 paper, 2007). An invasive adenocarcinoma that arises from the ovary and is characterized by the presence of malignant epithelial cells that contain intracytoplasmic mucin. "The non-pancreatic malignancies that were studied as a control group also yielded the data that SMAD4 shows negative immunoreactivity in colonic and pulmonary adenocarcinoma, however in 10% of breast ductal and ovarian mucinous adenocarcinoma, focal low positivity nuclear staining may be observed." (PMID 17587453, 2007).
ovarian tumors (1 paper, 2023). "There is negative reciprocal regulation between SMAD4 and FYN in ovarian tumors, and knockdown of SMAD4 results in elevated levels of FYN expression, and FYN activation leads to dissociation of cell-cell junctions and adhesion, resulting in increased tumor metastasis." (PMID 36740671, 2023).
Overgrowth (1 paper, 2024). Excessive postnatal growth which may comprise increased weight, increased length, and/or increased head circumference. "Cyclosporine-A-induced gingival overgrowth may be alleviated by inducing cell cycle arrest through the downregulation of CDC25A, CDK4/6, CYCLIN D, and pRB, along with the enhancement of SMAD3, SMAD4, and RB in gingival fibroblasts." (PMID 39727652, 2024).
Pan (1 paper, 2022).
pancreatic disease (1 paper, 2024). "Together, these additional analyses would deepen our understanding of the physiological and functional consequences of Smad4 deficiency, paving the way for potential therapeutic strategies tailored to genetic and sex-specific differences in pancreatic disease susceptibility." (PMID 39596873, 2024).
papillary adenocarcinoma (1 paper, 2008). A morphologic variant of adenocarcinoma. "In contrast, Smad4, which oligomerizes with Smad3 to form a trimeric protein complex, was more highly expressed in the papillary adenocarcinomas and may enhance the effect of Smad3 in these tumors." (PMID 18811984, 2008). "Similarly, the higher expression of Smad4 in the papillary adenocarcinoma tumors as potential compensation for the better expression of members the TGF-β-Smad3 pathway in the carcinomas has to be elucidated." (PMID 18811984, 2008).
Pca (1 paper, 2018). "Pathway and network analyses of SIRT1 were also generated based on neuroendocrine Pca cancer from TCGA database, and we found that SIRT1 could promote Pca progression via multiple pathways, including the HIF-1, SMAD4, and Akt pathways." (PMID 29416748, 2018).
peritoneal cancer (1 paper, 2026). A peritoneum cancer that is located in the inside of the abdomen. "Variables included peritoneal cancer index (PCI), tumor location, histology, HIPEC regimen, and KRAS/BRAF/SMAD4 status." (PMID 41595218, 2026).
peritoneal disease (1 paper, 2013). "Because of the unusual pattern of disease, PDAC was verified using a targeted exome panel of tissue from this patient’s peritoneal disease, which showed mutations in KRASp.G12V and SMAD4, further supporting the diagnosis of PDAC." (PMID 24004612, 2013).